RN7SKP298 (RN7SK pseudogene 298)
Gene: Miscellaneous RNA gene on chromosome 3 (166,670,029 to 166,670,122, reverse strand). Ensembl gene ENSG00000251759.
Homologues: Orthologues: chimpanzee 7SK (61% identical), mouse Gm56284 (59% identical). Paralogues in human: RN7SKP208 (72% identical), RN7SKP58 (72% identical), RN7SKP81 (72% identical), RN7SKP199 (71% identical), RN7SKP6 (71% identical), RN7SKP180 (70% identical), RN7SKP220 (70% identical), RN7SKP243 (70% identical), RN7SKP25 (70% identical), RN7SKP69 (70% identical), RN7SKP134 (69% identical), RN7SKP145 (69% identical), and 284 more.